MMP9 (matrix metallopeptidase 9)
Diseases named in the same sentence as MMP9 in open-access papers (continued):
Sharing a sentence is not in itself a finding about the gene and the disease.
morbid obesity (3 papers, 2015 to 2024). An excess of body weight, normally defined as an individual with a body mass index greater than 35 or a body weight greater than one hundred percent of ideal body weight. "Finally, as BS has been shown to effectively normalize all these parameters, we suggest that plasma MMP-9 and PBMCs AMPK activities might potentially be used as markers of cardiovascular risk in patients with morbid obesity." (PMID 31133882, 2019). "Medians of CD40L, adiponectin, MMP-2, MMP-9, and PAI-1 levels were higher in the group of morbid obesity patients as compared to the control group." (PMID 25261984, 2015).
mucositis (3 papers, 2018 to 2025). Mucositis is inflammation and damage of the mucous membranes lining the mouth and other parts of the gastrointestinal (GI) tract. "The increased MMP-9 staining rate in the control group suggests that the active immune response due to mucositis and the chronic inflammation process continuing in the COM period before tympanosclerosis increased MMP-9 expression." (PMID 40468054, 2025). "MMP-9 might be involved in the last healing phase in the 5-phase model of mucositis." (PMID 36499758, 2022).
myositis (3 papers, 2019 to 2024). "MMP-9 is recommended in the recent literature as an indirect marker to assess myositis severity in infected hosts." (PMID 39304848, 2024). "We first determined MMP9 mRNA levels in PBMCs isolated from 66 patients with myositis and healthy controls; a significant increase in MMP9 mRNA levels in patients with myositis compared to those in the healthy controls was observed (p < 0.001)." (PMID 31440381, 2019). "In this study, we aimed to determine the gene expression and serum level of MMP9 and their relationship with clinical features and serological parameters in myositis." (PMID 31440381, 2019). "Our results showed that MMP9 mRNA in peripheral blood mononuclear cells (PBMC) was upregulated in myositis patients compared to that in healthy controls." (PMID 31440381, 2019). "In our previous study, peripheral blood mononuclear cell (PBMC) mRNA transcription profiles were obtained from 24 myositis and 16 controls, showing that MMP9 mRNA levels were increased 4.63-fold in myositis patients compared with those in healthy controls (unpublished data)." (PMID 31440381, 2019). "Thirdly, myositis disease activity assessment tests such as Manual Muscle Test 8 (MMT8), MYOACT, and MITAX were not available for our cohort, making it difficult to associate the disease activity with MMP9 levels." (PMID 31440381, 2019). "This is the first report demonstrating that serum MMP9 levels are increased in myositis patients with anti-Jo1 antibodies and that this molecule may be involved in muscle inflammation rather than pulmonary damage or patient survival." (PMID 31440381, 2019). "To determine whether the upregulation of MMP9 mRNA level is reflected in the serum MMP9 levels as well, we analyzed circulating MMP9 levels in myositis patients and healthy controls." (PMID 31440381, 2019). "Therefore, in this study, we aimed to determine MMP9 gene expression and serum levels in patients with myositis and to explore whether MMP9 may serve as a biomarker for the extent of muscle, skin, and pulmonary damage in these patients." (PMID 31440381, 2019). "The distinct pattern of serum MMP9 perhaps clarifies the differences in pathophysiology between anti-Jo1 and anti-MDA5 in patients with myositis." (PMID 31440381, 2019). "Therefore, we hypothesize that, during myositis pathogenesis in patients with anti-Jo1 antibodies, MMP9 is released from neutrophils and PBMCs, cleaving type IV collagen in the basement membranes and allowing CD8+ T lymphocyte migration and invasion of the MHC class-I-expressing muscle fibers." (PMID 31440381, 2019). "The distinct pattern of serum MMP-9 level perhaps clarifies the differences in pathophysiology between anti-Jo-1 positive patients and anti-MDA5 positive patients in myositis." (PMID 31440381, 2019). "Myositis patients positive for anti-Jo1 antibodies exhibited significantly higher serum MMP9 than anti-MDA5 positive or antibody-negative patients and healthy controls." (PMID 31440381, 2019). "Neutrophil numbers were shown to be significantly increased in the anti-Jo1-positive myositis patients compared with those in the anti-MDA5-positive patients, which is consistent with the higher MMP9 level in anti-Jo1-positive sera than that in anti-MDA5-positive sera." (PMID 31440381, 2019). "In addition, serum MMP-9 levels were positively correlated with WBCs, neutrophils, CK, CRP, ESR, and LDH in myositis patients." (PMID 31440381, 2019). "In this study, we showed that MMP9 mRNA levels in the PBMCs of myositis patients, but not their serum protein levels, are significantly upregulated, which may contribute to the pathogenesis of IIM." (PMID 31440381, 2019). "However, the role of MMP9 in the pathogenesis of myositis has not been completely elucidated." (PMID 31440381, 2019). "However, no changes in MMP9 levels were detected in the sera of myositis patients." (PMID 31440381, 2019).
myositis (continued). "Circulating MMP9 levels were shown to be significantly elevated in patients with anti-Jo1 antibodies, but not in those with anti-MDA5 antibodies or antibody negative myositis patients." (PMID 31440381, 2019).
neonatal encephalopathy (3 papers, 2013 to 2025). "Indeed, in neonatal encephalopathy the levels of blood MMP-9 is about 10-fold higher than in non-encephalopathic controls." (PMID 23940734, 2013).
nephrotic syndrome (3 papers, 2019 to 2021). A collection of symptoms that include severe edema, proteinuria, and hypoalbuminemia; it is indicative of renal dysfunction. "Only MMP-9 has had its diagnostic and prognostic potentials studied but in only childhood forms nephrotic syndrome." (PMID 34707724, 2021). "In the current study, urinary MMP-9 in patients with nephrotic syndrome was not only higher but also correlated with proteinuria, an observation consistent with the findings in Henoch-Schonleinpurpura." (PMID 34707724, 2021). "MMP2 and MMP9 were found significantly elevated in the urine of patients with steroid-resistant nephrotic syndrome as compared to steroid-sensitive patients." (PMID 30921378, 2019). "As such, it remains to be determined if urinary nephrin and MMP-9, as individual markers or in combination with other biomarkers, could be important in an adult form of nephrotic syndrome such as IMN." (PMID 34707724, 2021).
neutropenia (3 papers, 2015 to 2016). A decrease in the number of neutrophils found in the blood. "It is also possible that MMP-9 activity during thrombus resolution is derived from neutrophils, as neutropenia is associated with impaired thrombus resolution and decreased intra-thrombus MMP-9." (PMID 26406902, 2015). "Moreover, because LCN2 is expressed in complex with MMP9 in neutrophils specifically, we asked whether the decline in serum levels might have reflected grave neutropenia during NACT and CRT." (PMID 27461255, 2016). "Our findings regarding MMP-9 as a mediator of thrombus resolution provide a unifying molecular mechanism for the changes in thrombus resolution and vein wall stiffening noted in a variety of prior studies, including those of gamma-interferon, uPA, neutropenia and plasmin inhibition." (PMID 26406902, 2015). "Treatment with an anti-intercellular adhesion molecule-1 (expressed on endothelial and immune cells) antibody, in addition to neutropenia, still produced low levels of MMP-9 expression, which was attributed to expression of MMP-9 by other cell types within the ischemic tissue." (PMID 26973468, 2016).
Nonalcoholic fatty liver disease (3 papers, 2023 to 2024). "Nonalcoholic fatty liver disease (NAFLD), often present in the obese patients, is associated with increased serum concentrations of MMP-2, MMP-9, TIMP-1, 2, TGF-beta concentrations." (PMID 38541059, 2024). "Aucubin also prevented the elevation of MMP-9, MCP-1, apoC-III, ICAM-1, VCAM-1, TNF-α, IL-1β, and IL-6 levels after stimulation by apoC-III in 3T3-L1 cells and in mice with tyloxapol-induced nonalcoholic fatty liver disease (NAFLD)." (PMID 37241895, 2023).
Oral leukoplakia (3 papers, 2018 to 2025). A thickened white patch on the oral mucosa that cannot be rubbed off. "Increased amounts of this and other macromolecules have been identified in precancerous lesions linked to the advancement of OSCC, while salivary concentrations of MMP-9 are reported to be higher in patients with oral leukoplakia compared to those with OSCC." (PMID 39911325, 2025). "MMP-9 was the marker that best correlated with the evolution from normal tissue to leukoplakia and neoplasm." (PMID 30539028, 2018).
oral lichen planus (3 papers, 2020 to 2024). Oral lichen planus is a chronic inflammatory oral condition of unknown aetiology characterized by T-cell-mediated chronic immune response and abnormal epithelial keratinization cycle. "MMP9 has a significant association with RAS, and COX2 is closely related to oral lichen planus." (PMID 32811507, 2020).
oropharyngeal squamous cell carcinoma (3 papers, 2019 to 2024). "The aim of this study was to evaluate the diagnostic usefulness of matrix metalloproteinase 3 (MMP 3) and matrix metalloproteinase 9 (MMP 9) in EBV positive oropharyngeal squamous cell carcinoma (OPSCC) patients." (PMID 38473807, 2024). "It seems that MMP-9 can inhibit the formation of metastases to lymph nodes in oropharyngeal squamous cell carcinoma." (PMID 31223594, 2019). "Although the expression of MMP9 was not determined, serum levels of MMP9 were found to be higher in patients with oropharyngeal squamous cell carcinoma with EBV infection than in EBV-negative patients." (PMID 39739829, 2024).
osteonecrosis (3 papers, 2016 to 2024). A none disease characterized by death of bone tissue due to a lack of blood supply. "Our data point to several potential candidate biomarkers of atraumatic osteonecrosis, with combined MMP-9 and VEGF-C being the most promising." (PMID 39590837, 2024). "MMPs levels were differently expressed in patients with osteonecrosis (elevated MMP-2 and decreased MMP-9) when compared with those free from osteonecrosis." (PMID 39590837, 2024). "MMP-9 predicted future osteonecrosis with higher sensitivity and specificity (area under the receiver operating characteristic curve [AUC] 0.84 [95% CI 0.84–0.99]; sensitivity/specificity 82%/75%; cutoff value ≤ 72,420 pg/mL) than osteopontin, MMP-2 and VEGF-C when taken alone." (PMID 39590837, 2024). "The combination of MMP-9 and VEGF-C circulating levels may serve to identify Gaucher disease patients at risk of osteonecrosis." (PMID 39590837, 2024). "Additionally, MMP-9 expression may serve as a marker of efficacy in the treatment of steroid-induced osteonecrosis using ACTH." (PMID 27637086, 2016). "Patients with osteonecrosis showed increased osteopontin and matrix metalloproteinase (MMP)-2 levels and decreased MMP-9 and vascular endothelial growth factor (VEGF)-C compared with those free from osteonecrosis." (PMID 39590837, 2024). "Matrix metalloproteinase-9 (MMP-9) and tissue inhibitor of metalloproteinases-1 (TIMP-1) are involved in the pathological mechanism of osteonecrosis of the femoral head (ONFH)." (PMID 36991363, 2023). "Last, high levels of MMP-9 along with an imbalance in the MMP-9/TIMP-1 ratio have been found in patients with idiopathic, alcohol- and steroid-induced nontraumatic osteonecrosis of the femoral head and correlated with the development and severity of osteonecrosis." (PMID 39590837, 2024).
ovarian dysfunction (3 papers, 2022 to 2024). The inability of the ovaries to function. "Among the genes we identified through coexpression of three datasets, PNPLA3, MVD, MMP9, oncostatin M (OSM), LCK, triggering receptor expressed on myeloid cells 1 (TREM1), FADS2, proprotein convertase subtilisin/kexin type 9 (PCSK9), and C3 are involved in lipid metabolism and ovarian dysfunction." (PMID 37537636, 2023).
pemphigoid (3 papers, 2021 to 2025). "An array of descriptive research linking metalloproteinases, particularly MMP-9, to pemphigoid has already been published but there remains a paucity of mechanistic studies." (PMID 34680139, 2021). "Early work reported 72 and 92 kd collagenases, now known as MMP-2 and MMP-9, in skin blisters of pemphigoid patients." (PMID 34680139, 2021). "In a landmark study in 1998, a genetically engineered mouse featuring targeted disruption of the gelatinase B (GB; MMP-9; 92 kD gelatinase) gene was used to explore the immunopathogenesis of pemphigoid." (PMID 34680139, 2021). "It has been hypothesized that metalloproteinase-9 (MMP-9) played an essential role in the pathogeneses of anti-lamγ1 pemphigoid." (PMID 35317170, 2022). "GB-deficient mice were resistant to the blistering effect of intracutaneous anti-mBP180 antibodies but when the mice were reconstituted with normal neutrophils, blister formation occurred, thus implicating neutrophil-derived GB/MMP-9 in the pathogenesis of experimental pemphigoid." (PMID 34680139, 2021). "MMP-9, for example, is essential for blister formation induced by anti-BP180 antibodies in mice, but pemphigoid patients develop autoantibodies against other junctional molecules including BP230, laminin 311, type VII collagen and α6β4 integrin." (PMID 34680139, 2021). "In particular, Plg-deficient mice reconstituted locally with the active form of MMP-9, but not the proenzyme form of MMP-9, develop pemphigoid, thus showing that the Plg/plasmin system is epistatic to MMP-9 activation and subsequent dermal-epidermal separation." (PMID 34680139, 2021). "Interestingly, only the proenzymes of MMP-2/9 could be found in lesional skin and in blister fluid of pemphigoid patients which contrasts to the situation in experimental mice where both the pro- and active forms of MMP-9 were detected in lesional and non-lesional skin samples." (PMID 34680139, 2021).
pemphigus vulgaris (3 papers, 2013 to 2025). Pemphigus is a group of chronic autoimmune skin diseases characterized by blister formations on the outer layer of the skin and the mucous membranes. "Animal models have also been used to study the role of MMP-9 in pemphigus vulgaris (PV), where administration of PV serum to mice resulted in increased MMP-9 expression." (PMID 41226358, 2025). "The results demonstrated that ADAM10 and MMP-9 activity is necessary for blister formation in experimental models of pemphigus vulgaris (PV) and BP, respectively." (PMID 34680139, 2021). "Although a potential role of MMP-9 in blister formation is currently discussed for Pemphigus vulgaris, a correlation with blister formation in EBS has never been considered so far." (PMID 23894602, 2013).
pneumococcal infection (3 papers, 2018 to 2025). Infections with bacteria of the species streptococcus pneumoniae. "Increased susceptibility to pneumococcal infection was described for MMP2 and MMP9 double knockout mice." (PMID 29119707, 2018). "MMP9 acted as a potentially protective factor against Streptococcus pneumonia infection." (PMID 36387401, 2022). "When we analyzed the expression of these and other MMPs, we observed that the pneumococcal infection indeed induced the expression of MMP‐2, MMP‐3, MMP‐8 and pro‐MMP9 in the respiratory tract of AIRmax mice." (PMID 29119707, 2018).
pouchitis (3 papers, 2017 to 2022). Acute inflammation in the intestinal mucosa of the continent ileal reservoir (or pouch) in patients who have undergone ileostomy and restorative proctocolectomy (proctocolectomy, restorative). "The level of fecal MMP-9 was the only marker correlating with the clinical symptoms of pouchitis, because it showed a significantly stronger correlation with the activity of UC than with that of CD." (PMID 29991970, 2018). "Significant correlation was also shown between fecal MMP-9 levels in patients with UC and pouchitis." (PMID 29991970, 2018). "Despite MMP-9 being elevated in both CD and UC, the performance of MMP-9 as a disease marker appears to be better in UC and pouchitis." (PMID 28522897, 2017).
Q fever (3 papers, 2019 to 2023). A bacterial infection caused by Coxiella burnetii. "It is possible that the overexpression of MMP-3 modulates MMP-9 expression in cells infected by C. burnetii, thereby contributing to the physiopathology of persistent Q fever." (PMID 37446087, 2023). "Additionally, we observed a larger MMP9+ proportion of macrophages in atherosclerotic AAAs than in Q fever AAAs (p=0.04)." (PMID 35137689, 2022).
radicular cyst (3 papers, 2020 to 2022). "The objective of this study was to determine the association of oxidative stress and the production of inflammatory mediators MMP-9 and interleukin 6 (IL-6) in systemic events in radicular cyst growth." (PMID 32467797, 2020). "Furthermore, MMP-9 was more markedly expressed in the OKCs’ epithelium compared to dentigerous cysts and radicular cysts." (PMID 35740900, 2022). "Studies suggested that MMP-9 is involved in the expansion of odontogenic cysts and it has been demonstrated that its higher expression in OKCs could explain the more aggressive biologic behavior compared to dentigerous and radicular cysts." (PMID 35740900, 2022).
rectal tumors (3 papers, 2006 to 2022). "In both colon and rectal tumors, MMP-2, MMP-9 and TIMP-1 protein levels were higher than in corresponding paired normal mucosa, while TIMP-2 level in tumors was significantly lower than in normal mucosa." (PMID 16916471, 2006).
renal dysfunction (3 papers, 2017 to 2025). "Another potential source for the elevated levels of total and active MMP-9 is the kidney via renal dysfunction." (PMID 41009467, 2025). "Patients with hypomagnesemia, vasopressor requirements, or biomarkers indicative of neuroinflammation (e.g., elevated IL-6, MMP9) may derive greater benefit, whereas those with hypermagnesemia or advanced renal dysfunction require cautious dosing." (PMID 40552120, 2025).
Salmonella Infections (3 papers, 2011 to 2024). Infections with bacteria of the genus SALMONELLA. "Furthermore, expression of mmp9, one of the most strongly induced markers after Salmonella infection, was only slightly up-regulated (1.4 times)." (PMID 22003892, 2011). "We used quantitative real-time PCR (qPCR) to determine the expression level of mmp-2, mmp-9 and e-cadherin in HCT116 cells during Salmonella infection and found that the expression level of mmp-2 and e-cadherin decreased, while the expression level of mmp-9 increased significantly." (PMID 36812247, 2023).
septic shock (3 papers, 2016 to 2024). Shock caused by infection; frequently caused by gram negative bacteria, although some cases have been caused by other bacteria, viruses, fungi, and protozoa; characterized by fever, chills, tachycardia, tachypnea, and hypotension. "The expression and activity of MMP-2 and MMP-9 was examined in patients with septic shock by FC and using a 3 compartment model (plasma, intraplatelet and platelet membrane) by gelatin zymography." (PMID 29734352, 2018). "They hypothesized that hemoperfusion therapy with PMX-F attenuated the increase in plasma MMP-9 concentrations in patients with septic shock by reducing plasma endotoxin." (PMID 27110221, 2016). "Quantitative Reverse Transcription Polymerase Chain Reaction validation was conducted for MMP8, MMP9, ARG1, HP, and CD163 across healthy controls, SIRS, and septic shock patient groups." (PMID 39560539, 2024).